RNU6-15P (RNA, U6 small nuclear 15, pseudogene)
Synonyms: RNU6-15
Gene: Small nuclear RNA gene on chromosome 10 (21,321,961 to 21,322,067, forward strand). Ensembl gene ENSG00000207264.
Homologues: Orthologues: rat U6 (99% identical), pig U6 (82% identical). Paralogues in human: RNU6-1 (98% identical), RNU6-2 (98% identical), RNU6-3P (98% identical), RNU6-4P (98% identical), RNU6-5P (98% identical), RNU6-6P (98% identical), RNU6-9 (98% identical), RNU6-10P (97% identical), RNU6-12P (97% identical), RNU6-13P (97% identical), RNU6-17P (97% identical), RNU6-18P (97% identical), and 1287 more.